DAP3 (death associated protein 3)
Diseases named in the same sentence as DAP3 in open-access papers (continued):
Sharing a sentence is not in itself a finding about the gene and the disease.
gout (1 paper, 2025). A condition characterized by painful swelling of the joints, which is caused by deposition of urate crystals. "The identification of DAP3 as a gout-associated gene suggests that mitochondrial health and apoptotic regulation are important factors in gout susceptibility and may represent potential targets for therapeutic intervention." (PMID 41075270, 2025).
inflammatory bowel disease (1 paper, 2020). A spectrum of small and large bowel inflammatory diseases of unknown etiology. "The genes DPH5 and DAP3 are co-expressed and associated with inflammatory bowel disease (IBD)." (PMID 32652930, 2020).
Intellectual disability (1 paper, 2025). "Patients with biallelic DAP3 variants present with profound SNHL, primary ovarian insufficiency, and intellectual disability." (PMID 41191133, 2025).
lung carcinoma (1 paper, 2023). "The authors demonstrated that low expression of DAP3 was associated with a good prognosis, emphasizing its potential value in the diagnosis and treatment of lung cancer." (PMID 38352299, 2023). "DAP3 knockdown in human lung cancer cell lines A549 and H1299 resulted in significantly reduced cell survival after radiotherapy." (PMID 38352299, 2023). "For example, DAP3 knockdown in a lung carcinoma cell line reduced the expression of radiotherapy-induced phosphorylated CHK1, which in turn led to radiotherapy-induced G2 arrest." (PMID 38352299, 2023). "In addition, the team examined the expression levels of DAP3 in both tissues and cell lines of human lung cancer and carried out a functional analysis to determine its biological role, which showed that DAP3 was significantly elevated in lung cancer tissues and cells." (PMID 38352299, 2023).
osteoporosis (1 paper, 2024). A condition of reduced bone mass, with decreased cortical thickness and a decrease in the number and size of the trabeculae of cancellous bone (but normal chemical composition), resulting in increased fracture incidence. "To address these deficiencies, we intend to conduct animal studies to enhance the reliability of the biomarkers and will continue monitoring the progress of ACAA2, DAP3, and BIK in relation to osteoporosis." (PMID 39130750, 2024).
Perrault syndrome (1 paper, 2025). Perrault syndrome (PS) is characterized by the association of ovarian dysgenesis in females with sensorineural hearing impairment. "Most known Perrault-syndrome-associated genes encode mitochondrial proteins with key roles in mitochondrial translation, which is consistent with DAP3 being a mitoribosomal SSU protein." (PMID 39701103, 2025). "In summary, we have identified five independent families with bi-allelic variants in DAP3 with a pleiotropic Perrault-syndrome-associated phenotype, expanding the genetic heterogeneity of Perrault syndrome and further emphasizing the importance of mitochondrial translation in health and disease." (PMID 39701103, 2025).
prostate carcinoma (1 paper, 2015). A carcinoma that arises from epithelial cells of the prostate gland. "To determine if DAPs are the effectors in poly I:C/IFN γ-induced apoptosis in prostate cancer cells, we examined the expression of DAP3 and 5 by Western blot analysis in the cells after IFN γ treatment." (PMID 26452032, 2015).
thymic carcinoma (1 paper, 2023). Thymic carcinoma (TC) is a type of thymic epithelial neoplasm characterized by a high malignant potential. "With the maturation of technology and further in-depth research, the involvement of DAP3 in the pathogenesis of thymic carcinoma will be revealed." (PMID 38352299, 2023). "To date, there have been few studies on DAP3 and thymic carcinoma." (PMID 38352299, 2023).
thymoma (1 paper, 2023). A neoplasm arising from the epithelial cells of the thymus. "The results confirmed that the expression levels of Abelson-related gene protein (Arg) and DAP3 were significantly higher in invasive thymomas (stage IV thymomas) than in stage I thymomas." (PMID 38352299, 2023).
tumor (17 papers, 2009 to 2025). "Clinically, high DAP3 expression was strongly associated with larger tumor size and elevated AFP levels, demonstrating good diagnostic value according to ROC analysis." (PMID 40051634, 2025). "According to previous studies, DAP3 is associated with tumor proliferation, metastasis, chemo-resistance, and radiotherapy resistance; however, the exact mechanism is unclear." (PMID 38352299, 2023). "Additionally, there was a notable difference in tumor mutation burden, suggesting that DAP3 expression levels may be associated with genomic instability and mutation rates." (PMID 40051634, 2025). "In summary, DAP3 plays a regulatory role in both the tumor microenvironment and genomic alterations within tumors." (PMID 40051634, 2025). "DAP3 was widely expressed in tumor cells, plasmacytoid dendritic cells (pDCs), and endothelial cells, with higher expression levels in tumor samples than in adjacent samples." (PMID 40051634, 2025). "Differential analysis between tumor and adjacent samples revealed that DAP3 was upregulated in pDCs." (PMID 40051634, 2025). "Metabolic heatmap analysis further demonstrated substantial activation of lipid metabolism, glycolysis, and oxidative phosphorylation in the DAP3+ group, particularly in recurrent tumor samples." (PMID 40051634, 2025). "To further investigate the distribution characteristics of DAP3 in the tumor microenvironment, we analyzed the relationships and gene characteristics among distinct cell populations through the integration of single-cell transcriptome data." (PMID 40051634, 2025). "Elevated levels of DAP3 were correlated with larger tumor size and higher alpha-fetoprotein (AFP) levels, and Cox analysis confirmed that DAP3 was a clinically independent prognostic marker." (PMID 40051634, 2025). "The chemiluminescence assay showed that mice injected with DAP3-KD Huh7 cells developed fewer metastases in the abdominal cavity and fewer tumour nodules in the intestine." (PMID 39080251, 2024). "Further study will shed light on the mechanism of DAP3-mediated drug resistance and tumor metastases, providing new strategies for the targeted treatment of tumors." (PMID 38352299, 2023). "In patients with high DAP3 expression, the infiltration of adaptive immune cells responsible for anti-tumor responses, such as B cells, T cells, CD8+ T cells, and cytotoxic cells, was significantly inhibited." (PMID 38352299, 2023). "In recent years, DAP3 has been found to be closely related to both tumor progression and the resistance of tumor cells to chemotherapy." (PMID 38352299, 2023). "The diverse and sometimes contrasting roles of DAP3 in different cells and different tumor types are summarized in this review." (PMID 38352299, 2023). "Contrasting roles of DAP3 in the tumour have progressed significantly in the past decades, however, a panel of questions remains to be answered." (PMID 38352299, 2023). "DAP3 was significantly upregulated in HCC tissues compared with adjacent non-tumor tissues which was consistent with the mRNA expression in TCGA." (PMID 36686684, 2022). "Consistently, our Kaplan–Meier analysis showed better survival in the low transcription group approaching significance, supporting tumor promotion influences of DAP3 on LUAD." (PMID 34026765, 2021). "Specifically we recorded a strong inverse correlation between mean copy number of DAP3 and tumour grade, Nottingham Prognostic Index, clinical stage, and clinical outcome." (PMID 25883535, 2015). "The number of samples used here in each type of tumours avoids trying to subdivide the tumour types on the basis of DAP3 expression, as this would reduce drastically the power of the statistical analysis for subtypes." (PMID 19536094, 2009). "The implication of DAP3 in apoptosis suggests a modulation of the expression of the protein in pathological contexts such as the development of tumours." (PMID 19536094, 2009).
tumor (continued). "In oncocytoma, the large majority of the cells show extensive mitochondrial biogenesis; these tumours thereby constitute an interesting model for the study of the expression and localisation of DAP3, as well as its function in the mitochondrial ribosome." (PMID 19536094, 2009). "Our results revealed significant upregulation of DAP3 expression in tumor samples." (PMID 40051634, 2025). "Furthermore, DAP3 expression is correlated with tumor stage and clinical outcomes in breast cancer patients." (PMID 40051634, 2025). "Death-associated protein 3 (DAP3), for instance, directly binds to the ADAR2 deaminase domain, disrupting its interaction with target transcripts and inhibiting editing activity, resulting in cancer cells escaping from editing-mediated tumor suppression." (PMID 41446042, 2025). "Finally, HCC cells were injected subcutaneously into the right groins of nude mice, and the DAP3-KD cells showed a significantly decreased ability to form tumours, accompanied by reduced Ki67 expression in nude mice." (PMID 39080251, 2024). "It is suggested that the expression of DAP3 may be related to the immunosuppressive tumor microenvironment of HCC." (PMID 38352299, 2023). "Research on DAP3 is currently underway, further investigation using advanced technology and multi-omics, the oncological role of DAP3 will eventually be elucidated, which will deepen our current understanding of the pathogenesis of tumour and provide evidence for developing novel therapies." (PMID 38352299, 2023). "DAP3 mRNA and protein expression also correlated with the tumor staging." (PMID 38352299, 2023). "The relationship between tumor promotion and cell apoptosis induced by DAP3 is still unclear." (PMID 38352299, 2023). "Since DAP3 is widely overexpressed in cancer cells, such DAP3-driven stabilization of WSB1 mRNA transcripts may be a key step in tumor initiation." (PMID 35379802, 2022). "These tumours may then be a good model to study specifically the function of DAP3 in the efficacy or fidelity of mitochondrial translation." (PMID 19536094, 2009). "Furthermore, differential analysis between primary and recurrent samples indicated significant upregulation of DAP3 in myeloid cells, suggesting that DAP3 may influence tumor development and progression." (PMID 40051634, 2025). "Indeed, several public GEO HCC datasets, such as GSE50579, GSE45411, GSE6764, and GSE20140, and the Clinical Proteomic Tumor Analysis Consortium (CPTAC) database also showed that DAP3 expression was higher in HCC tissues than in normal liver tissues or matched para-tumour samples." (PMID 39080251, 2024). "However, the presence of HML-10(DAP3) RNA in many tumor cell lines and the absence in most healthy tissues suggest that its upregulation may be a relevant feature in some human cancer diseases." (PMID 27980690, 2016). "Elevated DAP3 levels were correlated with increased AFP levels (P=0.044) and larger tumor size (P=0.024)." (PMID 40051634, 2025). "Then, we examined DAP3 expression in HCC and corresponding para-tumour tissues collected from both clinical patients and orthotopic HCC mouse models to further confirm the high DAP3 level in HCC in the analyses of those profiles." (PMID 39080251, 2024). "Likewise, DAP3 and DYNLL1 (apoptosis and cytoskeletal regulators) were overexpressed, underscoring the survival and migration advantages conferred to tumor cells." (PMID 41228302, 2025). "However, there was no discernible difference in the levels of DAP3 expressed by tumor tissues from various anatomical sites." (PMID 38352299, 2023). "Interestingly, aberrant DAP3 expression can facilitate tumor progression rather than promote apoptosis, although DAP3 was initially identified as a pro-apoptotic protein." (PMID 38352299, 2023).
cancer (16 papers, 2009 to 2025). A tumor composed of atypical neoplastic, often pleomorphic cells that invade other tissues. "For example, death-associated protein 3 (DAP3) is considered as an editing repressor, it can inhibit A-to-I editing in cancer cells by interfering with the homodimerization of ADAR1 and inhibiting the binding of ADAR2 to dsRNA." (PMID 38233935, 2024). "Previous studies showed that death associated protein 3 (DAP3) exerts a pivotal role in regulating apoptosis signaling of tumors, meanwhile, aberrant DAP3 expression is associated with the tumorigenesis and disease progression of various cancers." (PMID 38352299, 2023). "Suppression of apoptosis, as mediated by the HML-10(DAP3) RNA in HeLa cells, is a general hallmark of cancer cells." (PMID 27980690, 2016). "Additionally, DAP3 was found to be broadly overexpressed across various cancers, and linked to the severity of HCC lesions." (PMID 40051634, 2025). "For example, DAP3 is overexpressed in several cancer types, including human pancreatic cancer, invasive glioblastoma multiforme, and human thyroid tumors." (PMID 40051634, 2025). "In conclusion, the potential roles of DAP3 in carcinogenesis and cancer development warrant further investigation." (PMID 40051634, 2025). "Recently, DAP3 has also been linked to the regulation of RNA editing and splicing in the context of cancer, further highlighting DAP3’s broad range of functions." (PMID 39701103, 2025). "DAP3, an oncogene overexpressed across cancer types, alters the AS pattern of multiple splicing factors, thereby coordinately modulating the splicing of downstream genes via their respective splicing factors to promote cancer progression." (PMID 39550559, 2024). "Functional studies of WSB1 non-productive splicing provide evidence for a causal relationship between DAP3’s regulatory functions and tumorigenesis, providing key mechanistic insights into the role of DAP3 in splicing regulation in cancer development." (PMID 38352299, 2023). "Global splicing alterations were observed to play a role in carcinogenesis when DAP3 was overexpressed in several types of cancer." (PMID 38352299, 2023). "GSEA demonstrated that “G2M checkpoint,” “Mitotic spindle,” Myc targets,” “DNA repair” and “E2F targets,” which are related to cancer development and progression, were significantly activated in patients with high DAP3 expression." (PMID 38352299, 2023). "In multiple cancer types, DAP3 is a strong oncogenic protein that interacts with adenosine deaminase RNA specific (ADAR) proteins and inhibits A-to-I RNA editing." (PMID 38352299, 2023). "In sum, our findings demonstrate that DAP3 coordinates splicing regulatory networks to modulate global alternative splicing in cancer via both RNA–protein and protein–protein interactions." (PMID 35379802, 2022). "A pan-cancer analysis of alternative splicing across 33 TCGA cancer types identified DAP3-modulated mis-splicing events in multiple cancers, and some of which predict poor prognosis." (PMID 35379802, 2022). "Together, these findings provided solid evidence that DAP3 is a critical regulator of widespread alternative RNA splicing and dramatically reshapes transcriptome in cancer cells by altering thousands of alternative splicing events." (PMID 35379802, 2022). "By further investigations of functional importance of DAP3-driven splicing events in cancer using in vitro and in vivo models, our study provides critical mechanistic insights into the role of DAP3 in cancer development as a critical regulator of RNA splicing." (PMID 35379802, 2022). "In this study, we demonstrate that many DAP3-modulated splicing events were significantly altered in patients’ tumors and such changes demonstrate prognostic values in multiple cancer types." (PMID 35379802, 2022). "All these observations suggest that prevalent dysregulations of DAP3-modulated splicing events are clinically relevant to multiple cancer types." (PMID 35379802, 2022).
cancer (continued). "Of 20 experimentally validated DAP3-modulated splicing events, 18 of them (90%) were detected in almost all 33 TCGA cancer types with varying PSI values." (PMID 35379802, 2022). "Together, our work provides critical mechanistic insights into the splicing regulatory roles of DAP3 in cancer development." (PMID 35379802, 2022). "Here, we reveal a frequently overexpressed cancer-associated protein, DAP3, as a splicing regulatory RBP in cancer." (PMID 35379802, 2022). "It has been reported that DAP3 is overexpressed in a broad range of cancer types and appears to have strong oncogenic effect." (PMID 35379802, 2022). "In this study, we identify death-associated protein 3 (DAP3) as an RNA splicing regulator and uncovered its multilayered control of cancer transcriptome." (PMID 35379802, 2022). "This indicates a possible role in the regulation of DAP3 gene expression in cancer cells and some distinct tissues, including cervix, thyroid and uterus as well as epidermal keratinocytes and umbilical vein endothelial cells." (PMID 27980690, 2016). "This study highlights DAP3 as a significant factor in cancer prognosis and immune regulation, offering insights that could inform future therapeutic strategies." (PMID 40051634, 2025). "Considering the molecular mechanism of DAP3-regulated cancer development, new potential treatment strategies might be developed in the future." (PMID 38352299, 2023). "DAP3 suppresses adenosine-to-inosine (A-to-I) RNA epitome to further promote cancer progression." (PMID 37679418, 2023). "It has previously been shown that DAP3 interacts with RNA editing enzymes adenosine deaminases acting on RNA (ADARs) and functions as a potent repressor of adenosine-to-inosine (A-to-I) RNA editing in cancer cells." (PMID 35379802, 2022). "The RNA-binding preference of DAP3 towards the GAAGAA hexamer may partially explain why DAP3 tends to promote exon inclusion in both cancer cell lines." (PMID 35379802, 2022). "Notably, such widespread splicing changes modulated by DAP3 can be observed in multiple cancer types and are of clinical relevance and prognostic values." (PMID 35379802, 2022). "Besides transcriptional regulation by oncogenic transcription factors, such as c-Myc, HIF-1, and CREB-ATF36,37, our study provides another mechanism of WSB1 expression regulation in cancer cells, which is via DAP3-modulated alternative splicing." (PMID 35379802, 2022). "In our study, HAX1, FLAD1 and NDUFS2, which were positively correlated with DAP3, were reported to play a crucial in mitochondria which could regulate the progression in numerous cancers, indicating that DAP3 may be an important role in OXPHOS, which could affect HCC progression." (PMID 40051634, 2025). "Finally, functional analyses showed that DAP3 may promote HCC progression through multiple cancer-related pathways and suppress immune infiltration." (PMID 36686684, 2022). "Targeting DAP3-driven splicing events and blocking the splicing regulatory ability of DAP3 and/or specifically targeting DAP3-driven splicing events may hold great promise for cancer treatment." (PMID 35379802, 2022). "In this study, through application of eCLIP-Seq, RNA-Seq, and proteomics analyses, we characterize DAP3 as a widespread alternative splicing regulatory RBP which modulates thousands of splicing events and dissect its associated regulatory mechanisms and functional relevance to cancer." (PMID 35379802, 2022). "GSEA revealed that several cancer-related pathways, including the Wnt, apoptosis, TGF-beta, epithelial-mesenchymal transition, and PI3K pathways, were enriched in the high-DAP3 group." (PMID 40051634, 2025). "Thus, DAP3 may hold significant promise for cancer prognosis and treatment." (PMID 40051634, 2025). "Upregulation of DAP3 and CKAP2L are also known oncogenes that promote cancer development and resistance to radiation." (PMID 40135438, 2025).